HHIPL2 (HHIP like 2)
Synonyms: KIAA1822L; FLJ13840
Tractability: Antibody: UniProt places it where antibodies can reach, with high confidence; UniProt predicts a signal peptide or a membrane-spanning region; its Gene Ontology location is reachable by antibodies, with medium confidence.
Gene: Protein-coding gene on chromosome 1 (222,522,258 to 222,548,104, reverse strand). Ensembl gene ENSG00000143512.
Subcellular location: Secreted
Subcellular location (Human Protein Atlas): Mitochondria; Cytosol; Predicted to be secreted
Gene Ontology:
Molecular function: protein binding
Cellular component: extracellular region
Genetic constraint (gnomAD): Loss-of-function variants: 62 observed, 65.88 expected, observed/expected ratio (o/e) 0.94, 90% interval 0.77 to 1.16. The upper end of that interval is the gene's LOEUF score, 1.16, which puts it in group 5 of 6, group 1 being the genes least tolerant of losing a copy. Missense variants: 885 observed, 958.8 expected, observed/expected ratio (o/e) 0.92, 90% interval 0.87 to 0.98. Synonymous variants: 343 observed, 377.27 expected, observed/expected ratio (o/e) 0.91, 90% interval 0.83 to 0.99.
Homologues: Orthologues: chimpanzee HHIPL2 (99% identical), macaque HHIPL2 (97% identical), pig HHIPL2 (82% identical), mouse Hhipl2 (82% identical), rabbit HHIPL2 (82% identical), rat Hhipl2 (81% identical), dog HHIPL2 (80% identical), zebrafish hhipl2 (60% identical), tropical clawed frog hhipl2 (59% identical). Paralogues in human: HHIPL1 (54% identical), HHIP (27% identical).
Diseases named in the same sentence as HHIPL2 in open-access papers:
HHIPL2 is named in the same sentence as 6 diseases in open-access papers, as found by Europe PMC text mining. Sharing a sentence is not in itself a finding about the gene and the disease. The quoted sentences say what the papers report.
gastric cancer (2 papers, 2010 to 2021). A primary or metastatic malignant neoplasm involving the stomach. "HHIPL2 (HHIP-like 2) gene, amplified in the 1q41-q43.1 region, showed the highest copy number gain associated overexpression in gastric cancer according to the integrated microarray analysis (FC = 26.9)." (PMID 20187983, 2010). "This is the first study to report an association of HHIPL2 with gastric cancer." (PMID 20187983, 2010). "This association could possibly also offer an explanation for HHIPL2's role in gastric cancer." (PMID 20187983, 2010). "The overexpression was validated with the qRT-PCR analysis as HHIPL2 showed a 7.4-fold overexpression in gastric cancers compared to the normal tissues." (PMID 20187983, 2010). "Real-time qRT-PCR analysis showed that the expression of HHIPL2 was 7.4-fold higher in gastric cancer samples compared with the nonmalignant gastric tissues (p < 0.05)." (PMID 20187983, 2010).
cancer (3 papers, 2010 to 2021). A tumor composed of atypical neoplastic, often pleomorphic cells that invade other tissues. "Overexpression of HHIPL2 has not been previously associated with any cancers and its exact biological function is not known." (PMID 20187983, 2010). "In addition, the overexpression of HHILP2 was significantly associated with copy number gain (p < 0.05) as the expression of HHIPL2 was 17.4-fold higher in cancer samples with copy number gain of HHIPL2 (g1) than in cancer samples with normal copy number of this gene (g0)." (PMID 20187983, 2010). "HHIPL2, XPO1, SALRNA1, ZBTB45, ANP32AP1, ACTR3BP5, LOC100129138, GPR45, and CAB39L gene deletions were associated with non-cancer subjects without FCH (p < 0.05), while RAB9BP1, LOC101928523, and MALRD1 gene deletions were related to non-cancer patients with FCH (p < 0.05)." (PMID 33431054, 2021).
HHIPL2 also shares sentences with these, for which no sentence is quoted: cognitive deficits (1 paper); Infertility (1); melanoma (1); non-small cell lung carcinoma (1).